CRP (C-reactive protein)
Diseases named in the same sentence as CRP in open-access papers (continued):
Sharing a sentence is not in itself a finding about the gene and the disease.
anemia (continued). "Additionally, one study reported higher C-reactive protein levels in MI patients who had anemia indicating that chronic inflammation and cytokines such as transforming growth factor-beta may play a role in suppressing erythropoiesis and leading to anemia." (PMID 34527482, 2021). "Increased circulating hepcidin and sTfR, possibly secondary to increased pro-inflammatory C-reactive protein (CRP) and IL-6, might result in reduced iron release in the bloodstream, which triggers uncompensated anemia, much like in chronically diseased patients." (PMID 34573092, 2021). "The high prevalence of elevated CRP/AGP and reported malaria and diarrhoea suggest persistent and/or recurrent infections, which together with other parasitic worm diseases (i.e., helminths) lead to anaemia and micronutrient deficiencies (ID, VAD, and ZnD) and growth retardation." (PMID 34066852, 2021). "Inflammation and infections can cause anaemia and reduce the sensitivity of SF to detect ID but can be ruled out as substantial contributors in our study population because we did not include sick infants and the CRP concentrations were low in both groups." (PMID 31896356, 2020). "In addition, the effect of anemia, C-reactive protein (CRP), age, CD activity index (CDAI) or Mayo on PLTs was also analyzed." (PMID 32667493, 2020). "Upon admission, the full blood count showed mild normocytic anaemia (haemoglobin 10.8 g/dl), white blood cells and full blood count were within the normal range of values (in particular eosinophil count was 222 eosinophils/μl), C-reactive protein (CRP) was 5.20 mg/dl (normal values <1)." (PMID 31364552, 2019). "Although previous studies have identified several prognostic factors of poor outcome in advanced BCa, such as the presence of visceral metastasis, anemia, and C-reactive protein (CRP), it remains unknown whether they could be applied to the clinical assessment." (PMID 31815624, 2019). "Thus, based on the high correlation to levels of CRP and statistical association between VAD and anaemia, it is essential that children are adequately supplied with supplements and micronutrient rich foods especially if they have pre-existing infections or diseases." (PMID 29619077, 2018). "Therefore, anemia and the CRP level may be of value as indirect indicators of the lower limb ischemia that accompanies PAD." (PMID 27760183, 2016). "In addition to previously known risk factors including young age and long CPB time, preoperative anemia, elevated CRP levels on POD2, and an increase in hemoglobin concentrations from preoperative values were identified as new independent predictors of postoperative AKI in these patients." (PMID 27832187, 2016). "Therefore CRP level can be the predictor of anemia in this setting." (PMID 25901156, 2015). "In addition, CRP levels were significantly higher in both diagnostic groups with anemia than those in the population without anemia (P < 0.001 for CD and P = 0.009 for UC)." (PMID 25705682, 2015). "Laboratory findings are often nonspecific but may show evidence of GI malabsorption (e.g., low albumin, calcium, folate, iron, and red blood cell count), elevated erythrocyte sedimentation rate (ESR), elevated platelet counts, anemia, and increased acute phase reactants such as C-reactive protein." (PMID 26240765, 2015). "Despite eligibility criteria including only mild anemia, and the finding of normal mean ferritin levels at the beginning of the intervention at six months, normal iron status cannot be assumed due to the high levels of inflammatory markers, including elevated CRP levels for most subjects." (PMID 25493942, 2014). "She had severe anemia, total bilirubin level of 4.13 mg/dl, indirect bilirubin level of 3.33 mg/dl, elevated CA-125 level and elevated levels of inflammatory markers including the total white blood cell count, percentage of neutrophils, C-reactive protein (CRP) and fibrinogen." (PMID 24962423, 2014).
anemia (continued). "Although weight loss associated with decreased dietary intake is a large component of cancer-derived cachexia, other indicators (e.g., elevated c-reactive protein and dysfunctional immune response, anemia, abnormal metabolism and extreme fatigue) may also contribute to cancer-related cachexia." (PMID 25126097, 2014). "However, a recent study showed that binding of CRP to infected red blood cells (RBCs) increased the removal of damaged RBCs from the circulation, which could lead to a more pronounced anaemia." (PMID 19545442, 2009). "Laboratory evaluation showed anaemia, thrombocytosis, markedly elevated ESR and CRP, and high RF (288 U/mL) and ACPA (>300 U/mL)." (PMID 42100076, 2026). "Persistent or atypical musculoskeletal complaints-especially hip pain or back pain accompanied by anemia, high ESR, or high CRP-should prompt the consideration of neuroblastoma and early histopathological evaluation to avoid diagnostic delays." (PMID 41680912, 2026). "The laboratory results indicated anemia with a hemoglobin level of 7.2 g/dL, normal white cell counts as well as signs of inflammation, with an elevated ESR of 78 mm/h and CRP level of 298.7 mg/L." (PMID 40024178, 2025). "Anemia was the most prevalent abnormality (62%), followed by elevated inflammatory markers: ESR (35%) and CRP (31%)." (PMID 40234278, 2025). "From a public health perspective, our results advocate for integrated anaemia screening in obese populations that includes inflammation‐corrected iron markers (e.g., BRINDA‐adjusted ferritin, soluble transferrin receptor) and CRP or hepcidin measurements." (PMID 40968580, 2025). "Laboratory findings comprise elevated inflammatory markers C-reactive protein (CRP), erythrocyte sedimentation rate (ESR), leukocytosis, or normocytic anemia." (PMID 41030729, 2025). "Initial investigation finding revealed anemia with high ESR, high CRP, and neutrophilic leukocytosis." (PMID 40176882, 2025). "Among PSC, anemia was 36%; prevalences of MNDs were: iron, 57%; zinc, 67%; vitamin A, 19%; and B-12, 19%; with 39% elevated AGP or CRP." (PMID 40526587, 2025). "Initial blood tests revealed normocytic normochromic anemia, eosinophilia, and elevated inflammatory markers (ESR: erythrocyte sedimentation rate, CRP: C-reactive protein), with normal liver and kidney function tests." (PMID 41293340, 2025). "Laboratory findings showed a mild inflammatory response, with leukocytosis (14,000/mm3), elevated C-reactive protein (CRP) at 85 mg/L, and normocytic normochromic anemia (hemoglobin 10.2 g/dL)." (PMID 40255712, 2025). "PCa metastasis is directly linked to elevated IL-6 and TNF-α levels, which in turn drive an upsurge in CRP and FIB levels in the body, prevent iron from being absorbed as the building block of hemoglobin, and worsen anemia." (PMID 41142623, 2025). "Routine blood tests revealed elevated inflammatory markers (white blood cell count: 33730/μL; C-reactive protein [CRP]: 33.95 mg/dL), anemia (hemoglobin: 7.1 g/dL), and renal dysfunction (blood urea nitrogen [BUN]: 77.7 mg/dL; creatinine: 2.30 mg/dL)." (PMID 40667457, 2025). "The general well-being of the patient and anemia improved, ESR and CRP levels decreased in the follow-up." (PMID 39863703, 2025). "Blood tests revealed mild anaemia, lymphopenia (800/mm3), marked hypoeosinophilia (3/mm3), hepatocytolysis (ALT = 106 IU/L) and inflammatory syndrome (CRP = 16 mg/dL)." (PMID 40126322, 2025). "Although infective cases commonly present with elevated white blood cell counts (76.9%), anemia (92.9%), and increased erythrocyte sedimentation rate (ESR) and CRP." (PMID 41170455, 2025). "Blood tests revealed severe anemia, thrombocytopenia, Kidney Disease: Improving Global Outcomes (KDIGO) stage 1 acute kidney injury (AKI), and a mild elevation in C-reactive protein (CRP)." (PMID 40636661, 2025). "The laboratory findings included profound anaemia, elevated ANA and anti-dsDNA titres, low complement levels, and a raised ESR with a normal CRP." (PMID 40718204, 2025).
anemia (continued). "Initial laboratory findings revealed severe anemia (Hb 8 g/dL), leukopenia (WBC 2,150/μL), profound thrombocytopenia (platelets 30,000/μL), and elevated C-reactive protein (CRP) and troponin." (PMID 41431499, 2025). "All children had some evidence of inflammation (either increased CRP, ESR, or both) and an increased platelet count after the seventh day of fever, and a very high percentage exhibited anemia for their age." (PMID 40149999, 2025). "Initial workup showed anemia, thrombocytopenia, prolonged prothrombin time (PT), partial thromboplastin time (PTT), and elevated C-reactive protein (CRP) and erythrocyte sedimentation rate (ESR)." (PMID 39912015, 2025). "Laboratory investigations showed mild anemia, neutrophilic leukocytosis, mild procalcitonin (PCT) elevation, hypoxemia, and a normal C-reactive protein (CRP) level." (PMID 40918668, 2025). "Laboratory findings included normocytic normochromic anemia, elevated erythrocyte sedimentation rate (ESR), markedly increased C-reactive protein (CRP), and hyperferritinemia, with normal renal function and coagulation parameters." (PMID 41262827, 2025). "Laboratory tests showed elevated inflammatory markers (CRP: 7.07 mg/dL, WBC: 11,200/μL), microcytic anemia (hemoglobin: 7.8 g/dL), and thrombocytosis (platelets: 599,000/μL)." (PMID 41018483, 2025). "Key hematologic parameters in CTD include lymphopenia (common in SLE and other CTDs), thrombocytopenia (particularly in SLE and antiphospholipid syndrome), anemia of chronic disease (prevalent across CTDs), and elevated inflammatory markers (ESR, CRP)." (PMID 40700296, 2025). "Biochemical inflammatory syndrome (neutrophilia, elevated CRP and ESR, and frequently anemia and thrombocytosis) was the rule." (PMID 40843703, 2025). "Laboratory results showed elevated white blood cell count, C-reactive protein (CRP), and lactate dehydrogenase, along with anemia, hypoalbuminemia, and a marked rise in neutrophil-to-lymphocyte ratio and platelet-to-lymphocyte ratio." (PMID 41262899, 2025). "Anemia was reported in 72.7% of them, 9.1% had high levels of ferritin, and 18.2% had high ESR and C-reactive protein (CRP)." (PMID 39925559, 2025). "CRP is elevated in response to cytokines in an inflammatory state, whereas ESR can be increased in response to multiple factors related to HS, including anemia and inflammation." (PMID 41458786, 2025). "It has been suggested that patients can usually be assigned to groups of iron deficiency without anemia, iron deficiency anemia, renal anemia, anemia of inflammation, and non-iron-deficient non-anemia based on limited laboratory testing including blood count, ferritin levels, CRP, and creatinine." (PMID 41303295, 2025). "Treatment-induced tissue damage elevates circulating mediators (C-reactive protein [CRP], IL-6, interleukin-1β [IL-1β], interferon [IFN], tumor necrosis factor-α [TNF-α] potentially mediating central fatigue through anemia and cachexia pathways." (PMID 40496975, 2025). "Laboratory investigations showed mild anaemia (haemoglobin 11.9 g/dL) and elevated inflammatory markers (WBC 13 x 10^9/L, neutrophils 11.15 x 10^9/L, and C-reactive protein (CRP) 64 mg/L)." (PMID 41216104, 2025). "The outcomes were anemia [hemoglobin <10.5 g/dL (6–23 months) and hemoglobin <11 g/dL (24–59 months)] and VAD (retinol corrected by C-reactive protein <0.7 μmol/L)." (PMID 40165861, 2025). "The patient visited the local hospital, where laboratory tests showed a significant increase in inflammatory markers, including C-reactive protein (CRP) 154.5mg/L and erythrocyte sedimentation rate (ESR) 100mm/h, accompanied by mild anemia." (PMID 40917352, 2025). "CRP has been identified as an independent predictor of amputation, and large cohort studies further confirmed that elevated CRP and ESR, together with increased WBC and anemia, independently predict adverse outcomes." (PMID 41374452, 2025).
anemia (continued). "Laboratory tests showed anemia and thrombocytosis, increased inflammatory markers (erythrocyte sedimentation rate (ESR) and C-reactive protein (CRP)), increased serum urea and creatinine, hypoalbuminemia, and massive proteinuria." (PMID 40630350, 2025). "His laboratory results revealed anemia 125 gm/L (130–180 gm/L) but normal white blood cell (WBC) and C-reactive protein (CRP)." (PMID 41244980, 2025). "Laboratory findings include anemia; elevated ALT, AST, and total bilirubin raised lipase; and elevated CRP." (PMID 40731941, 2025). "Upon admission, blood tests revealed elevated inflammatory markers, including a C-reactive protein (CRP) level of 10.75 mg/dL and a D-dimer level of 4.2 μg/mL, alongside microcytic anemia." (PMID 40361969, 2025). "Lab work yielded an elevated brain natriuretic peptide (BNP), C-reactive protein (CRP), erythrocyte sedimentation rate (ESR), and alkaline phosphatase (ALP), with a mildly elevated white blood count and a mild normocytic anemia." (PMID 40225458, 2025). "Laboratory findings in our patient revealed mild anemia, elevated eosinophils, slightly low potassium levels, and mildly elevated ESR and CRP, indicating an inflammatory process." (PMID 39130991, 2024). "Blood tests revealed an elevated C-reactive protein (CRP, 161 mg/L) and erythrocyte sedimentation rate (ESR, 120 mm/h), and anaemia (Haemoglobin, 104 g/L)." (PMID 38473038, 2024). "Laboratory findings showed an elevation of White blood cell (WBC) count with a left shift of neutrophils, a high C-reactive protein (CRP) level, a high erythrocyte sedimentation rate (ESR), normocytic anemia, and renal dysfunction." (PMID 38552086, 2024). "He had a leukocyte count of 8.3 × 10∗9/L (normal range: 3.9–10 × 109/L), C-reactive protein (CRP) (98.3 mg/L) (normal range: <5 mg/L), normocytic anaemia (haemoglobin 91 g/L, MCV 91.9), normal liver-parameters, and slightly elevated D-dimer values (1.26 mg/L)." (PMID 38230406, 2024). "The results included mild anemia (hemoglobin: 9.1 g/dL), elevated eosinophils (12.2%), slightly low potassium levels (3.19 mmol/L), and mild elevation in ESR (20 mm/hr) and CRP (3 mg/L)." (PMID 39130991, 2024). "Our cases had a high level of CRP (median 31 mg/L), an elevated TLC count with a median of 16 (103/ mm3), mild anemia (9.4 g/dl ± 1.4), and a normal platelet count with a median of 368.5 (103/mm3)." (PMID 39294659, 2024). "The association between the presence of jaundice and complications (anemia and DIC) versus other factors (age, sex, CRP, and blood culture) (N = 71)." (PMID 38654771, 2024). "Initial investigations revealed mild anemia, elevated eosinophils, slightly low potassium levels, and mild elevation in erythrocyte sedimentation rate (ESR) and C-reactive protein (CRP), suggestive of an inflammatory process." (PMID 39130991, 2024). "Routine laboratory evaluation showed mild hypochromic normocytic anemia, a slight elevation in erythrocyte sedimentation rate (ESR) and C-reactive protein levels, and free and total PSA levels within the normal range." (PMID 38669404, 2024). "Laboratory and imaging tests revealed a decreased incidence of anemia, decreased albumin levels, elevated globulin levels, elevated LDH levels, elevated CRP levels, increased polyclonal serum immunoglobulin levels, and advanced disease stage." (PMID 38601148, 2024). "The current investigation demonstrates a significant correlation between the degree of CD activity as assessed by C-reactive protein (CRP) and Crohn's disease activity index (CDAI) and the severity of anemia." (PMID 39835061, 2024). "The laboratory test results indicated increased levels of C-reactive protein (CRP), mild thrombocytopenia, and anemia, as well as elevated procalcitonin and ferritin." (PMID 39493146, 2024).
anemia (continued). "As expected, the APLS cases showed anemia and thrombocytopenia when compared to healthy control however, they had higher N/L ratio, INR, PTT, ESR, and CRP which is mostly related to the ongoing chronic inflammatory-thrombotic pathology in APLS." (PMID 38549083, 2024). "In this study, patients typically displayed elevated NLR and CRP levels, decreased PAB and ALB levels, along with symptoms such as low-grade fever, malaise, and anemia." (PMID 39703501, 2024). "Laboratory markers such as elevated CRP or ESR, anemia, thrombocytopenia or thrombocytosis, hypoalbuminemia, and renal failure or proteinuria assist in the diagnosis process." (PMID 39161530, 2024). "In the HD group, the plasma KIM-1 levels showed a statistically notable correlation with inflammation (mean CRP: R = 0.28, p = 0.02; IL6: R = 0.36, p = 0.005) and with anemia (hematocrit: R = −0.5, p = −0.0316; hemoglobin: R = −0.5, p = 0.02)." (PMID 39200365, 2024). "Anaemia, as well as an elevated value of the ESHV in parallel with a CRP within normal limits, are supportive features for the diagnosis of SLE and are included in the 11 criteria for SLE classification, with a prevalence of involvement of 50–100%." (PMID 39194726, 2024). "Current research on clinical inflammatory factors affecting anemia mainly focuses on NLR, immune cells, cytokines and C-reactive protein (CRP)." (PMID 38799419, 2024). "Comparison of anemia, Hb, MCV, Ln SF, Ln SF/sTfR, and elevated CRP or HsCRP of all participants by BF% quartiles." (PMID 38544758, 2024). "The patient's investigation panel revealed leukopenia, anemia, elevated liver enzymes, and elevated erythrocyte sedimentation rate (ESR) and C-reactive protein (CRP) as well as significant elevation in creatinine kinase." (PMID 39318662, 2024). "The increase in WBC, CRP, LDH, and ESR values was positively correlated with the occurrence of anemia, while Alb was the opposite." (PMID 38886797, 2024). "Blood investigations showed microcytic hypochromic anemia, low normal platelet count and WBC counts, and significant elevation in ESR at 120 mm/hr and CRP at 60 mg/L but later improved after treatment." (PMID 39445278, 2024). "Laboratory tests performed on admission showed the presence of anemia (RBC 3.77*10^12/L, HGB 102 g/L, HCT 0.32) with a normal white blood cell count and mildly elevated C-reactive protein of 15.2 mg/L (normal value < 3 mg/L)." (PMID 38418948, 2024). "A statistically significant higher CRP (12.6 mg/L vs. 3.9 mg/l; p value < 0.001) and higher INR, (1.01 vs. 1.06; p value < 0.01) were found in the cohort of patients with preoperative anaemia." (PMID 38602554, 2024). "Tests like complete blood count (CBC) for anemia and markers like erythrocyte sedimentation rate (ESR) and C-reactive protein (CRP) assess disease activity and nutritional status." (PMID 39170992, 2024). "Despite treatment, she developed elevated C-reactive protein (CRP) and anemia after two years, leading to further investigations." (PMID 39070404, 2024). "The sarcopenia group showed a higher proportion of older women, with significant differences in anemia prevalence, calf circumference, gait speed, ALM, hand grip strength, and elevated CRP levels compared to the control group." (PMID 39502753, 2024). "C-reactive protein (CRP) levels (P = 0.002), anemia (P = 0.037), hypercalcemia (P = 0.023), and grade (P = 0.031) were independent predictors of serum LRG1 levels in ccRCC." (PMID 38658967, 2024). "He continued to show evidence of systemic inflammation with elevated CRP (peak 4.99 mg/dL; normal, 0–1 mg/dL), elevated ESR (peak 92 mm/hour; normal, 0–15 mm/hour), and normocytic anemia (9.9 g/dL; normal, 12.4–16.3 g/dL)." (PMID 37254165, 2023). "Our patient’s laboratory results revealed anemia, leukopenia, elevated LDH and CRP levels, a raised ESR rate, and positive ANA and anti-dsDNA tests." (PMID 37884991, 2023).